AZGP1P1 (AZGP1 pseudogene 1)
Gene: Transcribed unprocessed pseudogene on chromosome 7 (99,980,762 to 99,987,535, forward strand). Ensembl gene ENSG00000214313.
Diseases named in the same sentence as AZGP1P1 in open-access papers:
AZGP1P1 is named in the same sentence as 3 diseases in open-access papers, as found by Europe PMC text mining. Sharing a sentence is not in itself a finding about the gene and the disease.
AZGP1P1 shares sentences with these, for which no sentence is quoted: brain disorder (1 paper); breast carcinoma (1); cancer (1).